SH3BP5 (SH3 domain binding protein 5)
Description:
Functions as a guanine nucleotide exchange factor (GEF) with specificity for RAB11A and RAB25. Inhibits the auto- and transphosphorylation activity of BTK. Plays a negative regulatory role in BTK-related cytoplasmic signaling in B-cells. May be involved in BCR-induced apoptotic cell death.
Synonyms: SH3BP-5; SAB
Tractability: Small molecule: a structure with a bound ligand is known. Antibody: UniProt places it where antibodies can reach, with high confidence. PROTAC: ubiquitination databases record sites on it.
Gene: Protein-coding gene on chromosome 3 (15,254,353 to 15,341,368, reverse strand). Ensembl gene ENSG00000131370.
Subcellular location: Cytoplasmic vesicle membrane; Mitochondrion
Subcellular location (Human Protein Atlas): Nuclear bodies; Nucleoplasm
Gene Ontology:
Molecular function: guanyl-nucleotide exchange factor activity; protein binding; protein kinase inhibitor activity
Biological process: intracellular signal transduction; signal transduction
Cellular component: cytoplasmic vesicle membrane; nuclear body; nucleoplasm; cytoplasm; mitochondrion
Genetic constraint (gnomAD): Loss-of-function variants: 25 observed, 41.06 expected, observed/expected ratio (o/e) 0.61, 90% interval 0.44 to 0.85. The upper end of that interval is the gene's LOEUF score, 0.85, which puts it in group 3 of 6, group 1 being the genes least tolerant of losing a copy. Missense variants: 526 observed, 586.53 expected, observed/expected ratio (o/e) 0.9, 90% interval 0.83 to 0.96. Synonymous variants: 254 observed, 225.24 expected, observed/expected ratio (o/e) 1.13, 90% interval 1.02 to 1.25.
Homologues: Orthologues: chimpanzee SH3BP5 (100% identical), macaque SH3BP5 (98% identical), guinea pig SH3BP5 (93% identical), rat Mettl6 (93% identical), mouse Sh3bp5 (93% identical), rabbit SH3BP5 (90% identical), dog SH3BP5 (90% identical), pig SH3BP5 (87% identical), tropical clawed frog sh3bp5 (71% identical), zebrafish sh3bp5b (67% identical), zebrafish sh3bp5a (58% identical), Drosophila melanogaster pcs (29% identical), and 2 more. Paralogues in human: SH3BP5L (29% identical).
Diseases named in the same sentence as SH3BP5 in open-access papers:
SH3BP5 is named in the same sentence as 51 diseases in open-access papers, as found by Europe PMC text mining. Sharing a sentence is not in itself a finding about the gene and the disease. The quoted sentences say what the papers report.
COVID-19 (4 papers, 2021 to 2025). A disease caused by infection with severe acute respiratory syndrome coronavirus 2. "By 6 weeks post-inclusion (T2), COVID-19 hypermethylation of genes with lowest p-value included NXN, FMNL2, ZBTB46, SLC35F3, and SHQ1, and the hypomethylated genes included ELMO1, XBP1, GRIK1, TNFAIP8, and SH3BP5." (PMID 41227320, 2025).
preeclampsia (4 papers, 2022 to 2025). Preeclampsia is a hypertensive disorder of pregnancy that is characterized by new-onset hypertension with proteinuria presenting after 20 weeks of gestation, and depending on mild or severe forms may initially present with severe headache, visual disturbances, and hyperreflexia. "Further analysis of gene regulatory networks, including transcription factor–gene, gene–microRNA, and drug–gene interactions, revealed that seven hub genes (HK2, SRSF10, SOD1, ERO1L, IRF3, MME, and SH3BP5) were strongly associated with preeclampsia." (PMID 40966654, 2025). "Constructed a protein–protein interaction (PPI) network, identifying 10 hub genes, seven of which (HK2, SRSF10, SOD1, ERO1L, IRF3, MME, and SH3BP5) were strongly linked to preeclampsia." (PMID 40966654, 2025). "Then, we developed a novel diagnostic model using CPOX, DEGS1, and SH3BP5 and it showed a strong ability in screening preeclampsia samples from normal samples." (PMID 38259465, 2023). "The high expression of CPOX, DEGS1, and SH3BP5 may be associated with the pathogenesis of preeclampsia." (PMID 38259465, 2023). "In addition, we found that the levels of SH3BP5 were closely associated with several immune cells, highlighting its potential involved in immune microenvironment of preeclampsia." (PMID 38259465, 2023). "In this study, we found that the expressions of CPOX, DEGS1 and SH3BP5 were highly expressed in preeclampsia samples in GSE44711 and GSE75010 datasets and our cohort." (PMID 38259465, 2023). "Then, we performed LASSO and SVM-RFE and identified three critical diagnostic genes for preeclampsia, including CPOX, DEGS1 and SH3BP5." (PMID 38259465, 2023). "This suggested that in cases of preeclampsia, elevated levels of SH3BP5 may be accompanied by an increase or activation of these immune cell subgroups." (PMID 38259465, 2023). "Importantly, the results of RT-PCR confirmed the expressions of CPOX, DEGS1 and SH3BP5 were distinctly increased in preeclampsia samples compared with normal samples." (PMID 38259465, 2023). "However, further research is needed to gain a deeper understanding of the precise mechanisms by which SH3BP5 influenced immune cell subgroups in preeclampsia." (PMID 38259465, 2023). "In addition, we provided important evidences that SH3BP5 may be involved in preeclampsia progression via influencing immune microenvironment." (PMID 38259465, 2023). "Molecular docking analysis showed that HK2, SH3BP5, and SOD1 exhibited significant binding affinities with two preeclampsia drugs." (PMID 40966654, 2025). "However, the function of SH3BP5 in Preeclampsia progression remained unknown." (PMID 38259465, 2023). "Compared to normal samples, preeclampsia samples showed markedly elevated expression of CPOX, DEGS1, and SH3BP5, as determined by RT-PCR." (PMID 38259465, 2023).
leukemia (3 papers, 2019 to 2023). A malignant (clonal) hematologic disorder, involving hematopoietic stem cells and characterized by the presence of primitive or atypical myeloid or lymphoid cells in the bone marrow and the blood. "Abnormal expression or malfunction of SH3BP5 was associated with certain diseases and disease processes, including leukemia, lymphoma, and autoimmune diseases." (PMID 38259465, 2023). "This is the first demonstration of the SH3BP5 function in leukemia propagation and in the hematogenic system." (PMID 31546831, 2019). "Functionally, the knockdown of SH3BP5 expression markedly inhibits the cell viability and induced apoptosis of these leukemia cells." (PMID 31546831, 2019). "Further, the mRNA levels of SH3BP5 in leukemia cell lines were analyzed by quantitative RT-PCR." (PMID 31546831, 2019). "Together, these results suggest that SH3BP5 contributes to leukemia cell growth and survival." (PMID 31546831, 2019). "Our study might lead to a progression in the field of SH3BP5 function in promoting leukemia cell growth by JNK signaling pathway." (PMID 31546831, 2019). "Interestingly, the knockdown of SH3BP5 is known to induce apoptosis in leukemia cells." (PMID 34439361, 2021). "Notably, novel inhibitors targeting SH3BP5 may hold promise for human leukemia treatment, due to the lack of obvious physical defect of the SH3BP5 knockout mice." (PMID 31546831, 2019).
acute myeloid leukemia (2 papers, 2021 to 2022). Acute myeloid leukemia (AML) is a group of neoplasms arising from precursor cells committed to the myeloid cell-line differentiation. "High expression of SH3BP5 was proven to be associated with poor outcomes in acute myeloid leukemia patients." (PMID 36496360, 2022).
alcohol dependence (2 papers, 2012 to 2014). Physical and psychological dependence on alcohol. "A SNP downstream of SH3BP5 (rs1318937, 1000G CEU MAF = 0.108, 16 kb from rs1287467, r2 = 0.018) has shown evidence of association with alcohol dependence and alcohol and nicotine co-dependence." (PMID 24786987, 2014).
lung carcinoma (2 papers, 2024 to 2025). "SH3BP5 was identified as a downstream target of METTL3 that inhibited lung cancer invasion through regulating SH3BP5 mRNA stability in a YTHDF1-dependent manner." (PMID 39135791, 2024). "As result, we identified five target genes of metformin (RPS6KA5, RORA, SH3BP5, NUPR1, and CD40LG), which were significantly correlated with favorable prognosis and immune infiltration in lung cancer patients." (PMID 39135791, 2024). "The bioinformatics analysis identified five favorable prognostic MTGs (RPS6KA5, RORA, SH3BP5, NUPR1, and CD40LG) for NSCLC patients, all of which was downregulated in lung cancer tissues as compared with normal tissues." (PMID 39135791, 2024).
adrenocortical carcinoma (1 paper, 2022). "Moreover, SH3BP5 was identified as an invasion- and proliferation-related gene of adrenocortical carcinoma." (PMID 36496360, 2022).
amyotrophic lateral sclerosis (1 paper, 2021). Amyotrophic lateral sclerosis (ALS) is a neurodegenerative disease characterized by progressive muscular paralysis reflecting degeneration of motor neurons in the primary motor cortex, corticospinal tracts, brainstem and spinal cord. "Immunohistochemical analysis showed that the levels of intraneuronal SH3BP5 were significantly reduced in neurons of AD cortices, compared with those of amyotrophic lateral sclerosis (ALS) cortices (unpaired t-test, p = 0.0256)." (PMID 33441550, 2021).
ischemic stroke (1 paper, 2018). A stroke disorder caused by obstruction of blood flow to the brain, due to thrombotic (local blood clot formation) or embolic (due to a blood clot or other material traveling from another site) event. "We have screened autoantibody levels in the sera of patients with ischemic stroke and report TUBB2C, ATP2B4, BMP-1, DHPS, and SH3BP5 as possible antigens that may be implicated in the development of stroke." (PMID 29507658, 2018).
nicotine dependence (1 paper, 2017). Physical and psychological dependence on nicotine. "SNPs annotated to genes previously associated to obesity traits (LINGO2, NELL1) and neurological disorders (schizophrenia (ACSM1, KIF26B, NALCN)), and alcohol and nicotine dependence (LINGO, SH3BP5) were found among Prudent reported dietary pattern score associated-SNPs." (PMID 28644415, 2017).
steatosis (1 paper, 2022). Increased lipid within the cytoplasm of cells. "Decreased hepatic SAB (SH3BP5) expression by Sab knockdown or knockout decreases ROS and decreases the stress kinase JNK activation in established experimental models of steatosis and steatohepatitis." (PMID 36009582, 2022).
cancer (5 papers, 2018 to 2026). A tumor composed of atypical neoplastic, often pleomorphic cells that invade other tissues. "Seven of the identified HGs (HK2, SRSF10, SOD1, ERO1L, IRF3, MME, and SH3BP5) were associated with PE and various carcinomas." (PMID 40966654, 2025). "In the present study, we found that SH3BP5-mediated activation JNK contributes to survival of cancer cells." (PMID 31546831, 2019). "Contradictory, our results suggested that SH3BP5-mediated activation of JNK contributes to survival of cancer cells." (PMID 31546831, 2019). "SH3BP5-high tumors displayed broad suppression of cycle activity, including priming and activation, immune cell recruitment (e.g., B cells and Treg cells), and the recognition of cancer cells by T cells (p < 0.05)." (PMID 40993727, 2025). "mRNA expression analysis revealed that FOXM1 and MCM3 were upregulated, whereas SH3BP5 and PAPSS2 were downregulated in cancer tissues compared with normal tissues." (PMID 41750695, 2026).
tumor (3 papers, 2022 to 2025). "Additionally, SH3BP5 was significantly associated with cell proliferation, suggesting its involvement in regulating tumor cell growth." (PMID 40993727, 2025). "SH3BP5-high tumors exhibited reduced stromal/immune scores and increased tumor purity, aligning with its role in suppressing anti-tumor immunity." (PMID 40993727, 2025). "This metabolic reprogramming not only promotes tumor cell survival but also fosters an immune escape-permissive environment, underscoring SH3BP5’s dual role in metabolic adaptation and immune modulation." (PMID 40993727, 2025). "The study examines the role of SH3BP5 in tumor metabolism and its potential implications for disease stratification." (PMID 40993727, 2025). "However, the precise role of SH3BP5 in tumor progression and its impact on disease treatment remain unclear, which is the primary focus of this study." (PMID 40993727, 2025). "Furthermore, emerging evidence indicates that SH3BP5 influences tumor stemness by modulating the BCR and WNT signaling pathways, while its interaction with the JNK axis may contribute to resistance to chemotherapy and immunotherapy." (PMID 40993727, 2025). "Functional studies showed that SH3BP5 knockdown significantly suppressed DLBCL cell proliferation, induced apoptosis, and reduced tumor cell viability in vitro." (PMID 40993727, 2025). "A multi-dimensional analysis of SH3BP5 expression was performed across DLBCL subtypes, integrating transcriptomic, proteomic, and clinical datasets to assess its correlation with immune infiltration, tumor metabolism, and patient prognosis." (PMID 40993727, 2025). "Our data demonstrate that SH3BP5-high DLBCL tumors exhibit significantly reduced infiltration of anti-tumor immune effectors, such as CD8 + T cells, alongside decreased stromal-immune scores and increased tumor purity." (PMID 40993727, 2025). "This suggests that its targets, such as SH3BP5, NBEA, ZBTB20, ESR2, and ESR1, may escape miR-204-mediated repression, potentially leading to their overexpression, which could promote tumor growth and metastasis." (PMID 41009685, 2025).
infection (2 papers, 2023). The state of being infected such as from the introduction of a foreign agent such as serum, vaccine, antigenic substance or organism. "Likewise, B cell differentiation genes (BCL10, CD72, FOS, PTPRC, SH3BP5, PTPN6, etc.)were also downregulated throughout the infection, correlating with the drop of B cell numbers at D8." (PMID 37146079, 2023).
neurological disease (2 papers, 2017 to 2025). "Brain-specific SH3BP5-mediated signaling pathways are implicated in neuronal activity by influencing mitochondrial physiology through interacting kinases, potentially correlating with neuronal damage and susceptibility to neurological disease during TBI." (PMID 40149729, 2025).
neurodegenerative disease (1 paper, 2025). A disorder of the central nervous system characterized by gradual and progressive loss of neural tissue and neurologic function. "The mitochondrial scaffold protein SH3BP5 is involved in signaling pathways related to mitochondrial dysfunction and apoptosis, making it an important signaling platform for neurodegenerative diseases." (PMID 40149729, 2025).
SH3BP5 also shares sentences with these, for which no sentence is quoted: dementia (2 papers); diabetes (2); liver fibrosis (2); membrane nephropathy (2); arteriosclerosis (1); Ataxia (1); autoimmune disease (1); B‐cell lymphoma (1); cocaine dependence (1); cognitive decline (1); dependence (1); diffuse large B-cell lymphoma (1); glioma (1); Glomerular sclerosis (1); hepatitis A (1); Hepatitis B (1); Hyperglycemia (1); Hypertension (1); influenza (1); liver disease (1); lymphoma (1); measles (1); meningococcal infection (1); metabolic dysfunction-associated steatohepatitis (1); Microscopic hematuria (1); mumps (1); Myocardial fibrosis (1); myocardial infarction (1); Obesity (1); opiate dependence (1).
A further 5 diseases each share a sentence with SH3BP5 in 1 paper.